PDE6A (phosphodiesterase 6A)
Description:
Catalytic alpha subunit of the rod-specific cGMP phosphodiesterase (PDE6) complex, which hydrolyzes 3',5'-cyclic GMP in the phototransduction cascade. The PDE6 holoenzyme consists of two catalytic subunits (PDE6A and PDE6B) and two inhibitory gamma subunits (PDE6G). Light-activated GNAT1 relieves gamma subunit-mediated inhibition, enabling the catalytic subunits to hydrolyze cGMP and thereby mediate visual signal transduction and amplification. Decreased cytosolic cGMP levels result in closure of cGMP-gated cation channels at the plasma membrane, leading to rod photoreceptor hyperpolarization (By similarity).
Synonyms: PDEA; RP43; CGPR-A
Tractability: Small molecule: an approved drug acts on it; a high-quality ligand is known; it belongs to a druggable protein family. Antibody: UniProt places it where antibodies can reach, with high confidence; its Gene Ontology location is reachable by antibodies, with high confidence. PROTAC: a small molecule that binds it is known.
Target class: Phosphodiesterase 6; Phosphodiesterase 6A; Phosphodiesterase; Enzyme
Gene: Protein-coding gene on chromosome 5 (149,857,953 to 149,945,287, reverse strand). Ensembl gene ENSG00000132915.
Subcellular location: Photoreceptor outer segment membrane; Cell membrane
Pathways (Reactome):
Sensory Perception: Activation of the phototransduction cascade; Inactivation, recovery and regulation of the phototransduction cascade
Signal Transduction: Ca2+ pathway
Gene Ontology:
Molecular function: 3',5'-cyclic-GMP phosphodiesterase activity; 3',5'-cyclic-AMP phosphodiesterase activity; 3',5'-cyclic-nucleotide phosphodiesterase activity; phosphoric diester hydrolase activity
Biological process: visual perception; negative regulation of cAMP/PKA signal transduction; retina development in camera-type eye; transducin-mediated opsin signaling pathway; signal transduction
Cellular component: rod photoreceptor disc membrane; photoreceptor disc membrane; photoreceptor outer segment membrane; plasma membrane
Genetic constraint (gnomAD): Loss-of-function variants: 68 observed, 93.69 expected, observed/expected ratio (o/e) 0.73, 90% interval 0.6 to 0.89. The upper end of that interval is the gene's LOEUF score, 0.89, which puts it in group 3 of 6, group 1 being the genes least tolerant of losing a copy. Missense variants: 984 observed, 1,064 expected, observed/expected ratio (o/e) 0.92, 90% interval 0.88 to 0.98. Synonymous variants: 369 observed, 385.07 expected, observed/expected ratio (o/e) 0.96, 90% interval 0.88 to 1.04.
Gene-disease validity (ClinGen):
ClinGen rates the evidence that PDE6A causes each of these diseases.
PDE6A-related retinopathy (autosomal recessive): Definitive. Any retinopathy caused by variants in the PDE6A gene.
Homologues: Orthologues: macaque PDE6A (99% identical), dog PDE6A (95% identical), mouse Pde6a (95% identical), rat Pde6a (95% identical), rabbit PDE6A (94% identical), guinea pig PDE6A (94% identical), pig PDE6A (91% identical), chimpanzee PDE6A (88% identical), tropical clawed frog pde6a (78% identical), Drosophila melanogaster Pde11 (29% identical), Drosophila melanogaster Pde8 (13% identical), Caenorhabditis elegans pde-6 (12% identical), and 1 more. Paralogues in human: PDE6B (71% identical), PDE6C (63% identical), PDE11A (30% identical), PDE5A (29% identical), PDE2A (23% identical), PDE10A (23% identical), PDE4A (18% identical), PDE4D (17% identical), PDE3A (17% identical), PDE4B (16% identical), PDE4C (16% identical), PDE1C (16% identical), and 8 more.
Diseases named in the same sentence as PDE6A in open-access papers:
PDE6A is named in the same sentence as 25 diseases in open-access papers, as found by Europe PMC text mining. Sharing a sentence is not in itself a finding about the gene and the disease. The quoted sentences say what the papers report.
retinitis pigmentosa (14 papers, 2016 to 2025). Retinitis pigmentosa (RP) is an inherited retinal dystrophy leading to progressive loss of the photoreceptors and retinal pigment epithelium and resulting in blindness usually after several decades. "Subsequently, a 10-fold lower dose of 5 × 1010 vg was chosen as the starting dose for the ongoing phase I/II clinical trial for retinitis pigmentosa due to PDE6A mutations." (PMID 39878701, 2025). "We evaluated in nonhuman primates (NHPs) the ocular safety and toxicology of a novel AAV gene therapy targeting retinitis pigmentosa caused by mutations in PDE6A, which has since been used in a phase I/II clinical trial (NCT04611503)." (PMID 39878701, 2025). "and PDE6A –Retinal dystrophy (HGF: 9.40) with recessive MOI (known to cause recessive retinitis pigmentosa)." (PMID 32271766, 2020). "Similarly, deducing the allele-level variant architecture in an individual (subject 16) with PDE6A-associated retinitis pigmentosa (RP) allowed reassignment of c.1646T>C, p.Leu549Pro to likely pathogenic." (PMID 39264853, 2024). "Mutations in PDE6B were reported previously to cause autosomal dominant congenital stationary night blindness or autosomal recessive retinitis pigmentosa, while mutations in PDE6A were reported to cause retinitis pigmentosa that is inherited in an autosomal recessive manner only (OMIM)." (PMID 35033039, 2022). "The mutation of PDE6A causes retinitis pigmentosa 43, which affects the function of PDE6B." (PMID 35033039, 2022). "Furthermore, mutation analysis of 17 retinitis-pigmentosa-specific missense mutations in PDE6A showed that 9 mutations were also present in COSMIC databases, out of which 8 were found to be slightly destabilizing in terms of their ΔΔG values." (PMID 30962868, 2019). "The purpose of this study is to identify novel variants in PDE6A and PDE6B genes and present its phenotypes in patients with retinitis pigmentosa in Chinese families." (PMID 35033039, 2022). "This is the first description of successful gene augmentation for Pde6a retinitis pigmentosa in a large animal model." (PMID 28676737, 2017). "Recently, a loss-of-function mutant of a rod-specific alpha subunit of pde6 (pde6a) in larval zebrafish revealed that the model recapitulates the human retinitis pigmentosa phenotype, with a preliminary degeneration of rods followed by a subsequent loss of some cones." (PMID 37745292, 2023). "We find that a retinitis-pigmentosa causing mutation in human PDE6G leads to the expression of a 3′UTR-encoded frameshift-isoform that is both destabilized and shows an inhibited ability to interact with its known binding partners PDE6A and PDE6B." (PMID 32727563, 2020). "Despite mutations in the rod phosphodiesterase 6-alpha (PDE6A) gene being well-recognized as a cause of human retinitis pigmentosa, no definitive treatments have been developed to treat this blinding disease." (PMID 28676737, 2017).
retinal degeneration (9 papers, 2014 to 2025). Degeneration of the retina. "Of the five IRD genes with significant effects, three (Aipl1, Pde6a, Pde6b) are associated with a recessive retinal degeneration in humans." (PMID 41282224, 2025). "Our study addresses these two problems by showing that PARP activity is a common denominator in retinal degeneration caused by three different point mutations in the Pde6a gene." (PMID 27551530, 2016). "In Mfrprd6 eyes, a significant 1.5- to 2.0-fold decrease was observed among transcripts of genes linked to retinal degeneration, including those involved in visual cycle (Rpe65, Lrat, Rgr), phototransduction (Pde6a, Guca1b, Rgs9), and photoreceptor disc morphogenesis (Rpgrip1 and Fscn2)." (PMID 25357075, 2014). "Interestingly, variants in rhodopsin, Pde6a, Pde6b, Prph2 and Rom1 are associated with inherited retinal degeneration in both humans and mice, and their downregulation may underlie the retinal degenerative phenotype observed in Hbs1ltm1a/tm1a mice." (PMID 38966981, 2024). "Therefore, this study offers a proof‐of‐concept demonstration for the treatment of Pde6a‐related retinal degeneration using BE and PE systems." (PMID 39297417, 2024). "None of the pathogenic mutations in genes related to congenital retinoschisis (RS1) or retinal degeneration (USH2A, ABCA4, PDE6A, PDE6B, RPE65, etc.)were detected by targeted exome sequencing or WGS." (PMID 36980859, 2023). "Even when the correct window of opportunity was chosen (i.e. a treatment time-point and duration that showed an effect), PJ34 treatment did not halt retinal degeneration completely, in any of the four Pde6a mutants." (PMID 27551530, 2016).
Retinal dystrophy (4 papers, 2020 to 2025). Retinal dystrophy is an abnormality of the retina associated with a hereditary process. "This explains why pathogenic variants in PDE6A (OMIM #180071), PDE6B (OMIM #180072) and PDE6G (OMIM #180073) cause predominantly rod-involving retinal dystrophies, whereas pathogenic variants in PDE6C and PDE6H (OMIM #600827 and #601190) lead to retinal dystrophies which predominantly affect cones." (PMID 37433860, 2023).
autosomal recessive retinitis pigmentosa (3 papers, 2017 to 2023). Autosomal recessive retinitis pigmentosa (RP) is an autosomally recessive inherited retinal dystrophy leading to progressive loss of the photoreceptors and retinal pigment epithelium and resulting in blindness usually after several decades. "Pathogenic mutations in the PDE6B gene are known to cause autosomal dominant congenital stationary night blindness (adCSNB) or autosomal recessive retinitis pigmentosa (arRP); however, similar mutations in PDE6A are known to cause only autosomal recessive retinitis pigmentosa (arRP)." (PMID 36959549, 2023). "For example, mutations in PDE6A and PDE6B are associated with autosomal recessive retinitis pigmentosa." (PMID 29088834, 2017).
Leber congenital amaurosis (3 papers, 2015 to 2024). Leber congenital amaurosis (LCA) is a retinal dystrophy defined by blindness and responses to electrophysiological stimulation (Ganzfeld electroretinogram (ERG)) below threshold, associated with severe visual impairment within the first year of life. "The consanguineous RP352 family (which was originally diagnosed with Leber congenital amaurosis at the Tongren Eye Center) was found to carry a novel homozygous small deletion c.1268delT (p.L423*) in PDE6A (NM_000440)." (PMID 26496393, 2015). "Naturally occurring canine models exist for several IRDs, some of which have contributed to gene augmentation therapies in humans, such as the Rpe65 model for Leber congenital amaurosis (LCA), and the Pde6a and Pde6b models for autosomal recessive RP phenotypes." (PMID 34828377, 2021).
retinal disease (3 papers, 2007 to 2014). "Because the affected dogs did not share common alleles, we excluded single, fully penetrant mutations in six known canine retinal disease genes: BEST1, PDE6B and PDE6A, RPE65, NPHP4, and CNGB3." (PMID 25198798, 2014).
Atrophy (2 papers, 2024). Any weakening or degeneration, especially through lack of use. "Fundus autofluorescence (FAF) imaging showed focal areas of decreased signal at the fovea, similar to areas of atrophy in an age matched patient with PDE6A-RP." (PMID 38745847, 2024). "To elucidate whether this atrophy is a consequence of inherent properties of AAV, or if it is related to the surgical trauma of subretinal delivery, we analyzed data from an Investigational New Drug–enabling study for PDE6A gene therapy in nonhuman primates." (PMID 38881604, 2024).
breast carcinoma (2 papers, 2013 to 2025). "PDE6A was minimally expressed at a significant level only in MB-231 cells, and not in any of the other breast cancer cells." (PMID 24683528, 2013).
night blindness (2 papers, 2022 to 2023). Inability to see clearly in dim light. "Nevertheless, the phenotypic analysis revealed no substantial differences between the two groups except for night blindness as a symptom that was noted to be more prevalent in the PDE6A-linked RP than in the PDE6B group." (PMID 36959549, 2023). "We identified five RP patients with PDE6A variants and three with PDE6B variants, all our patients reported night blindness as the first sign appeared from birth." (PMID 35033039, 2022). "Phenotypic analysis revealed no substantial differences between the two groups except for night blindness as a symptom that was noted to be more prevalent in the PDE6A than PDE6B group by another group." (PMID 35033039, 2022).
Retinal atrophy (2 papers, 2024 to 2025). A nonspecific term denoting wasting, especially as a result of degeneration, of the retinal pigment epithelium (RPE) and neurosensory retinal cells. "The analysis of the molecular basis of Progressive Retinal Atrophy in dogs, particularly the RCD3 type caused by mutations in the PDE6A gene, is important for several reasons." (PMID 40428296, 2025). "Subretinal injection of AAV.PDE6A induced dose-dependent, progressive retinal atrophy at the site of injection." (PMID 38881604, 2024).
cone-rod dystrophy (1 paper, 2018). Inherited retinal dystrophies that belong to the group of pigmentary retinopathies. "Here, we present the initial results of a pilot study targeting zebrafish orthologs of five human genes linked to RP: PDE6A, PDE6B, PDE6G, ABCA4, and RHO (note, ABCA4 is also linked to cone-rod dystrophy)." (PMID 30186835, 2018).
glaucoma (1 paper, 2021). Increased pressure in the eyeball due to obstruction of the outflow of aqueous humor. "These 13 glaucoma-associated genes can be divided into three functional groups: phototransduction-related genes (GNGT1, OPN1SW, PDE6A, PDC, CRX, CNGB1, GUCY2F), glutamate receptor (GR) genes (GRIN2B, GRIK3, GRIK4), and 5-hydroxytryptamine receptor (HTR) genes (HTR1A, HTR1E, HTR7)." (PMID 33874942, 2021).
glioma (1 paper, 2021). A benign or malignant brain and spinal cord tumor that arises from glial cells (astrocytes, oligodendrocytes, ependymal cells). "High DEGs in grade II gliomas included NNMT, MFAP5, APCDD1L-AS1, C7orf57, HP, SERPINA5, and LTF and some highly downregulated DEGs included ABCA4, PDE6A, GRP, RD3, and TMEM72." (PMID 33948562, 2021).
retinoblastoma (1 paper, 2025). A malignant tumor that originates in the nuclear layer of the retina. "The highest agreement between RNA and protein level was observed for DDB2, CHAF1B, and POLD1, which were upregulated in retinoblastoma, and RHO, PDE6A, and CRABP1, which were downregulated." (PMID 40395327, 2025).
Usher syndrome (1 paper, 2018). A syndromic diseae characterized by the association of sensorineural deafness (usually congenital) with retinitis pigmentosa and progressive vision loss. "While Usher syndrome etiology is classically regarded as stemming from genes that do not contain PDE6A, PDE6B, or PDE6G, researchers have yet to identify whether the mechanisms that underlie vision loss in Usher syndrome are identical to those present in non-syndromic RP." (PMID 29472945, 2018).
tumor (4 papers, 2013 to 2025). "However, PDE6A knockdown did not suppress TNBC tumor cell growth or invasion, demonstrating that PDE6A does not play a functional role in TNBC." (PMID 40961924, 2025).
cancer (3 papers, 2019 to 2022). A tumor composed of atypical neoplastic, often pleomorphic cells that invade other tissues. "In colorectal cancer samples PDE6A and PDE6B genes were found to be hyper-mutated genes and all the mutations are enlisted in OASIS, a multi-omic data repository for cancer." (PMID 30962868, 2019).
PDE6A also shares sentences with these, for which no sentence is quoted: infection (4 papers); achromatopsia (1); Blindness (1); congenital retinoschisis (1); listeriosis (1); macular dystrophies (1); microphthalmia (1); neurodegenerative disease (1).